RNU1-6P (RNA, U1 small nuclear 6, pseudogene)
Synonyms: RNU1-6
Gene: Small nuclear RNA gene on chromosome 1 (16,534,081 to 16,534,224, reverse strand). Ensembl gene ENSG00000277344.
Homologues: Orthologues: chimpanzee U1 (96% identical), macaque U1 (92% identical), dog U1 (70% identical), guinea pig U1 (65% identical). Paralogues in human: U1 (97% identical), RNU1-5P (97% identical), RNU1-143P (92% identical), RNU1-153P (92% identical), RNU1-68P (92% identical), U1 (92% identical), RNU1-19P (77% identical), RNU1-1 (76% identical), RNU1-2 (76% identical), RNU1-27P (76% identical), RNU1-28P (76% identical), RNU1-3 (76% identical), and 134 more.